BST2 (bone marrow stromal cell antigen 2)
Diseases named in the same sentence as BST2 in open-access papers (continued):
Sharing a sentence is not in itself a finding about the gene and the disease.
infection (89 papers, 2010 to 2026). The state of being infected such as from the introduction of a foreign agent such as serum, vaccine, antigenic substance or organism. "SARS-CoV-2 viral like particles (VLPs) were used to examine for effects on BST2 caused by productive and abortive infections." (PMID 38190411, 2024). "The impact of BST-2 deficiency on LCMV-specific T cell function at day 8 post-infection was quite significant." (PMID 30028868, 2018). "LncRNA Bst2/BISPR is activated upon infection with the recombinant influenza virus that is deficient in the interferon (IFN) response blocking and after treatment with type I IFN." (PMID 30052469, 2018). "Influenza nonstructural protein 1 (NS1) also antagonizes BST‐2 by averting IFN signaling and infection with this virus results in loss of BST‐2 steady state levels." (PMID 27042298, 2016). "Next, cells isolated from WT or BST-2-deficient mice were inoculated with IAV at different multiplicities of infection (MOI) and the percentage of IAV-infected cells was determined 6–8 hours later by detection of newly synthesized viral nucleoprotein (NP)." (PMID 26566124, 2015). "Infection of BST-2-deficient mice with Chikungunya virus (CHIKV) results in increased viremia, in accordance with its capacity to tether CHIKV in vitro." (PMID 26566124, 2015). "Regardless, our infection studies revealed similar kinetics of weight loss and viral replication in BST-2-deficient and WT mice." (PMID 26566124, 2015). "Since BST2 is a protein that recycles between the cell surface and intracellular compartments it was conceivable that enhanced infection of BST2-expressing fibroblasts was caused by BST2 enhancing viral entry." (PMID 22072961, 2011). "Moreover, the demonstration of RSV’s counteraction to BST2 restriction in cells close to its natural targets underlines the relevance of these data and paves the way for new strategies of infection control." (PMID 39561185, 2024). "Similarly, infection of BST-2 deficient mice with Moloney murine leukemia virus elicits enhanced viral titers." (PMID 26566124, 2015). "Cells expressing BST2 became more susceptible to infection with HCMV." (PMID 22072961, 2011). "The observed loss of the m6A modification in BISPR post-infection may indicate a decrease in m6A-mediated decay, therefore enhancing transcript stability and enabling its upregulation and cis-mediated regulation of BST2." (PMID 41267684, 2025). "Indeed, the computed top DEG, typifying each cluster on day 3 in the effector phase of infection, hosted several interferon-induced anti-viral genes (Irf1, Irf7, Ifrd1, Socs1, Socs3, Ifit1, Bst2, and Isg15) as well as genes associated with mature resident Trm cells (Cd69, Nfkbid, Brd2, FosB)." (PMID 35260804, 2022). "As anticipated, overexpression of BST-2 led to decreased expression of viral proteins and mRNAs in infected cells across multiple time points following infection." (PMID 40871369, 2025). "Next, we examined the effect of BST-2 on viral replication at distinct time intervals following infection." (PMID 40871369, 2025). "When focusing on the genes detected during SARS-CoV-1 and -2 infection, we found that at 24 and 48 hpi, two ISGs, i.e., bone marrow stromal cell antigen 2 (BST2, also known as CD317, HM1." (PMID 39874350, 2025). "Host antiviral factors showed distinct effects toward viral cell-free and cell-cell infections, such as BST-2 and IFITM." (PMID 39868869, 2025). "Overall, we found that BST2, ZBP1, CXCL11, and IFITM1 are associated with infection with SARS-CoV-1, SARS-CoV-2 WA-1 and Omicron BA.1, hepatitis C virus, HIV, and influenza virus." (PMID 39874350, 2025). "BST2 can respond to infection by inducing proinflammatory responses via NF-κb signaling pathway activation." (PMID 40429912, 2025). "BST2 is an antiviral protein that inhibits the release and spread of many viruses and is upregulated as part of the innate immune defense against infections." (PMID 40429912, 2025).
infection (continued). "Then cells were infected with a recombinant RSV virus expressing luciferase (RSV-Luc) as a reporter gene and a luciferase assay was performed 48h post infection to quantify the effect of BST2 overexpression in a multicycle infection assay." (PMID 39561185, 2024). "Lung virus titration, based on a plaque-forming assay, also showed that significantly more virus remained at the infection site in the Bst2−/− DC-vaccinated group than in the Bst2+/+ DC-vaccinated group." (PMID 39796009, 2024). "Consistent with our experiments in A549-ACE2-BST2 cells, SARS-CoV-2 productive infection downregulated IFN-induced BST2." (PMID 38190411, 2024). "We also showed an increase of ubiquitinated BST2 during infection and a decrease of BST2 presence in CD63 compartments compared to non-infected cells." (PMID 39561185, 2024). "In summary, these results demonstrate that SARS-CoV-2-mediated downregulation of BST2 is relevant to infection, and that Omicron is more efficient at counteracting BST2 than early isolates." (PMID 38190411, 2024). "Bst2 mRNA expression was upregulated by MA10 infection and downregulated in the kidneys of the MA10 + JAKi group compared with those of the MA10 group." (PMID 38634132, 2024). "During intravaginal infection with HSV-2, pDC depletion using anti-Bst2 antibodies enhanced infection-induced mortality, especially during prophylactic treatment of animals with CpG." (PMID 38777879, 2024). "We showed that BST2 silencing resulted in a significant rise in viral production during multi-cycle infection, suggesting an inhibitory role during the late steps of RSV’s multiplication cycle." (PMID 39561185, 2024). "Progressing to 16 h post-infection, the expression of genes related to lipid raft formation, such as BST2 appeared, was upregulated, and the expression of the antiviral gene RSAD2 was upregulated." (PMID 39872814, 2024). "Remarkably, we noticed that BST2 induction was augmented in infections with Omicron at MOI = 0.1, which is consistent with recent findings showing that Omicron enhances interferon promoter activity." (PMID 38190411, 2024). "In a model of HEp–2 cells where the BST2 gene is expressed in normal growth conditions, we observed a downregulation of BST2 cell surface expression under infection." (PMID 39561185, 2024). "Altogether, these results suggest that the virus also managed to counteract BST2 in a more physiological model of infection." (PMID 39561185, 2024). "We found that BST2 silencing 2 h after infection abolished the IL-27-mediated increase in the expression of BST-2/Tetherin and, in addition, weakened the anti-HIV-1 effect of IL-27." (PMID 36602368, 2023). "BST-2/Tetherin contributes to the IL-27-induced suppression of HIV-1 production when this cytokine is added to infected cells 2 h after infection." (PMID 36602368, 2023). "IL-27 inhibited HIV-1 replication when added to cells 2 h after infection, promoting the prototypical BST-2/Tetherin-induced virion accumulation at the cell membrane of HIV-1-infected PBMCs." (PMID 36602368, 2023). "In fact, silencing the BST-2/Tetherin gene permitted IL-27 to function again as a potent HIV-1 inhibitory factor, similar to when BST2-sufficient infected PBMCs were exposed to this cytokine shortly after infection." (PMID 36602368, 2023). "Apart from its role as a viral tether, BST2 can activate NF-κB pathaway to fend off host pathogen infections." (PMID 37495116, 2023). "Altogether, our results show that IL-27 is able to inhibit HIV-1 production when added to PBMCs just after infection and that the innate restriction factor BST-2/Tetherin is a critical mediator of this anti-HIV-1 effect." (PMID 36602368, 2023). "In the transcriptome results of this study, the encoding genes of BST2, STAT1, and hnRNPA1 were only upregulated in the PEDV 85-7C40 infection process." (PMID 35762780, 2022). "Surprisingly, BST2 is indispensable for the infection, proliferation, and transmission of certain viruses, including HIV-1." (PMID 36176574, 2022).
infection (continued). "Methylation begins to increase at 12 months’ post infection, and by 36 months post infection, the mean expression of BST-2 dips to pre-infection levels while methylation is considerably higher than that at pre-infection timepoint." (PMID 34025670, 2021). "These ISGs, which include MX1, MX2 and BST2, were found to be upregulated in hPIV1-infected cells by at least 7-fold compared to hPIV3 infected cells at both early and late time points after infection." (PMID 34529742, 2021). "At the pre-infection time point, BST-2 expression levels are relatively low, with modest methylation of the gene." (PMID 34025670, 2021). "Previous studies have demonstrated that BST-2 surface levels are elevated during acute infection and then progressively decrease throughout the stages of infection, even after initiation of ART." (PMID 34025670, 2021). "Taken together, these data show that BST-2 is a gene induced by innate immunity after the sensing of infection by TLRs." (PMID 31426525, 2019). "The role and mechanisms of restriction, which have been well defined for a classical cell-free infection, leave an open window for debates when a restriction (for example, BST2-mediated) tackles cell-to-cell viral transmission." (PMID 31027334, 2019). "Given the complex bitropic life cycle of morbilliviruses in SLAMF1-positive immune cells and nectin-4 positive epithelia, the role of restriction factors, including BST2, in the innate response to infection is an area of increasing interest." (PMID 31366072, 2019). "Nevertheless, the clear-cut results that we obtained using BST2 null cells confirmed the role of BST2 in the enhancement of cell-to-cell infection." (PMID 31027334, 2019). "One striking observation from our BST2 transfection and MeV-GFP infection experiments was a reduced number of large GFP-positive syncytia in BST2 transfected cells as compared with the pcDNA3.1 control." (PMID 31366072, 2019). "Treatment of PBMC in vitro with IFN-α or TLR agonists increased the expression of BST-2 to levels similar to those found during infection in vivo." (PMID 31426525, 2019). "For this we transfected 293T cells with either BST-2 or control plasmid, followed by infection with LCMV (moi = 0.01)." (PMID 30028868, 2018). "Prior to infection, most splenic immune cell populations were comparable between WT and BST-2 KO mice." (PMID 30028868, 2018). "By studying the lymphocytic choriomeningitis virus (LCMV) model of infection, we sought insights into how BST-2 shapes the early viral distribution and immunological defense against a virus during the establishment of persistence." (PMID 30028868, 2018). "Numbers of GFP positive cells were similar in both Huh7.5.1 and Huh7.5.1/BST2 cells at 24 hrs p.i. following challenge with different multiplicities of r3LCMV/GFP infection (moi = 0.001, 0.01, and 0.1)." (PMID 30028868, 2018). "293T cells were transfected with plasmids expressing EBOV VP40 alone or together with BST-2, followed by infection with rLCMV/Z-FLAG (moi = 5)." (PMID 30028868, 2018). "In human monocyte derived macrophages (MDM), TLR3 induces the expression of BST‐2 upon infection with HIV‐1." (PMID 27042298, 2016). "Most importantly, HIV-1 release and infection are markedly inhibited by IMB-LA in BST-2 expressing cells." (PMID 26669976, 2015). "Compared to individual pre-infection levels, the relative BST2 mRNA levels at 24 weeks post infection (wpi) were on average about threefold higher." (PMID 26554913, 2015). "Our results from the cross-sectional studies suggest an induction of BST2 together with MX1 during the asymptomatic phase of infection." (PMID 26554913, 2015). "This was also the case following infection with IBV, where BST-2-deficient mice display reduced viral titers in the lung." (PMID 26566124, 2015).
infection (continued). "As an example, treatment of SIV-infected animals with a type I interferon receptor antagonist blunted the infection induced BST2 induction, led to increased viral replication during acute infection and accelerated disease progression." (PMID 26554913, 2015). "Infection with HKx31 provokes a significant increase in IFNα in the respiratory tract and consequently elicits conditions under which BST-2 expression is likely to be elevated." (PMID 26566124, 2015). "BST2 is regulated by exogenous cues like type I interferons and intrinsic signal cascades after sensing infections through TLRs, both convening at transactivation of BST2 through IRFs." (PMID 26554913, 2015). "Most importantly, HIV-1 release and infection is inhibited by IMB-LA only in BST-2-expressing cells." (PMID 26669976, 2015). "In all experiments and at different phases of infection, BST2 transcription but also protein expression was positively correlated with plasma viral load." (PMID 26554913, 2015). "In extension to these previous studies, we were also able to study for the first time the relationship between BST2 levels and disease course by combining data from several infection experiments." (PMID 26554913, 2015). "Again, BST2 mRNA levels were significantly increased compared to pre-infection levels (p < 0.01) and correlated significantly with viral load (p < 0.05) (data not shown)." (PMID 26554913, 2015). "Compared to pre-infection levels, we found increased BST2 expression in PBMC, purified CD4+ lymphocytes and CD14+ monocytes of SIV-infected animals, which correlated with viral load." (PMID 26554913, 2015). "In fact, we show that lncBST2/BISPR and BST2 are induced after infection with HCV or influenza and VSV mutant viruses that activate the IFN response." (PMID 25620967, 2014). "They further suggest that BST2 restriction represents a major barrier during early infection when the predominant mode of viral transmission is likely to occur through cell-free virus." (PMID 24195843, 2013). "In this present study, we used the beta-retrovirus, mouse mammary tumor virus (MMTV) as a model to examine the role of mouse BST-2 in host infection in vivo." (PMID 22284121, 2012). "Results show that while cells transfected with BST-2 plasmid show lower levels of MMTV DNA across board, transfection of 100 ng of BST-2 plasmid results in about 60% lower infection, indicating that BST-2 restricts MMTV replication in a dose dependent manner." (PMID 22284121, 2012). "We chose to silence lymph node BST-2 because lymphocytes play a critical role in the in vivo infection with MMTV and other retroviruses such as HIV-1; and in the absence of a knockout model, siRNA provides the best alternative." (PMID 22284121, 2012). "To determine the role of endogenous BST-2 in virus replication in vivo, we administered either a control siRNA, or siRNA that targets BST-2 mRNA to mice, followed by infection with MMTV." (PMID 22284121, 2012). "Forty-eight hours after infection, the cells were incubated in medium containing cycloheximide to monitor the degradation of BST-2 with time." (PMID 21304933, 2011). "In both cases, BST2 at the cell surface will enhance the virion binding and entry of viruses into the host cells and thereby infection by virus." (PMID 22072961, 2011). "Since this increased infection was observed prior to the onset of viral gene expression and even when virus was UV-inactivated, we concluded that BST2 enhanced viral entry." (PMID 22072961, 2011). "AD169-infection of THP-1 cells induced endogenous BST-2 consistent with the increase of BST-2 observed in AD169-infected fibroblasts." (PMID 22072961, 2011). "Tetherin (also known as BST-2) is a recently identified restriction factor that traps viruses at the cell-surface, preventing their release and thus infection of other cells." (PMID 20386718, 2010).
infection (continued). "Viral genes like HIV-1 vpu and simian immunodeficiency virus nef/env could downregulate BST-2 cell surface display and enhance viral cell-free infection." (PMID 39868869, 2025). "We confirmed this result by imaging BST2 in RSV infected cells at 24h post infection." (PMID 39561185, 2024). "Alternatively, as we observed an accumulation of BST2 in the TGN, we could postulate that the recycling of BST2 to the cell surface could be altered in response to infection, rerouting BST2 to the TGN, leading to its degradation." (PMID 39561185, 2024). "The depletion of BST2 leads to an improvement of RSV viral production 48h post infection (half-log difference); the limited effect observed could be explained by the natural downregulation of BST2 by the virus which occurs even in the control cells." (PMID 39561185, 2024). "Interestingly, at 48h post infection we observed almost half-log difference in viral production between cells treated with BST2 siRNA and cells treated with control siRNA." (PMID 39561185, 2024). "As BST2 is known to prevent infection by tethering viral particles, we hypothesized that multicycle infection would be a sensitive strategy to reveal a BST2 inhibitory effect." (PMID 39561185, 2024). "We hypothesized that the increased ubiquitinylation of BST2 during infection accelerated its degradation." (PMID 39561185, 2024). "Cell adhesion is a critical factor in cell migration, which prompted us to investigate whether BST2-mediated adhesion plays a role in the migration of antigen-presenting cells (APCs) from the site of infection to the draining lymph nodes (dLNs)." (PMID 39796009, 2024). "Additionally, upregulation of PDCA-1/BST2 expression (commonly expressed by pDCs and B cells) was consistent in both mouse genotypes during acute infection." (PMID 37795093, 2023). "•BST2 expression is up-regulated during the early phase of infection." (PMID 37495116, 2023). "Further studies are needed to elucidate whether IL-27 exhibits similar divergent roles in other HIV-1 target cells, such as macrophages and dendritic cells, and if so, to search for the contribution of BST-2/Tetherin in those infection settings." (PMID 36602368, 2023). "In addition to virion tethering, BST2 can respond to infection by HIV-1 or other enveloped viruses by inducing proinflammatory responses via NF-κb signaling pathway activation." (PMID 36176574, 2022). "Methods to analyze the level of infection and BST2 expression are various, which could explain the discrepancies in the results." (PMID 34835003, 2021). "In the context of CXCL10 and BST2 roles during liver fluke infection, they may participate in the host defense mechanism such as the immune response at the early stage of the infection." (PMID 33879231, 2021). "The levels of BST2 were also increased, mostly around the peak of infection." (PMID 32119719, 2020). "The upregulation of BST-2 observed during this stage of infection could impact the capacity of Vpu to target multiple TM proteins." (PMID 31213558, 2019). "Thus, BST2-tethered viral particles mediated cell coculture infection more efficiently and at a higher level of multiplicity than diffusely distributed virions." (PMID 31027334, 2019). "BST-2 (or, tetherin) is an antiviral protein that inhibits the release and spread of many enveloped viruses and is upregulated as part of the innate immune defense against infections." (PMID 30028868, 2018). "Interestingly, we observed elevated BST-2 expression in the marginal zone region where LCMV Cl-13 localized early after infection." (PMID 30028868, 2018). "Based on the anatomical expression pattern of BST-2 at early times after Cl-13 infection, we postulated that BST-2 might contribute to the early confinement of LCMV within the splenic marginal zone." (PMID 30028868, 2018).